GRM3 (glutamate metabotropic receptor 3)
Description:
G protein-coupled receptor for glutamate. Ligand binding causes a conformation change that triggers signaling via guanine nucleotide-binding proteins (G proteins) and modulates the activity of down-stream effectors. Signaling inhibits adenylate cyclase activity.
Synonyms: mGluR3; GPRC1C; mGlu3; GLUR3
Tractability: Small molecule: a drug acting on it is in phase 2 or 3 trials; a structure with a bound ligand is known; a high-quality ligand is known; it belongs to a druggable protein family. Antibody: UniProt places it where antibodies can reach, with high confidence; its Gene Ontology location is reachable by antibodies, with high confidence; UniProt predicts a signal peptide or a membrane-spanning region. PROTAC: ubiquitination databases record sites on it; its protein half-life has been measured; a small molecule that binds it is known.
Target class: Family C G protein-coupled receptor; Metabotropic glutamate receptor; Small molecule receptor (family C GPCR); Membrane receptor; Neurotransmitter receptor (family C GPCR)
Chemical probes: ML289, ML337
Safety:
Unwanted effects reported when the protein is acted on. In parentheses: how it was acted on, where the effect was seen, and who reports it.
worsening of working memory (source: ClinPGx)
Gene: Protein-coding gene on chromosome 7 (86,643,909 to 86,864,884, forward strand). Ensembl gene ENSG00000198822.
Subcellular location: Cell membrane
Pathways (Reactome):
Signal Transduction: Class C/3 (Metabotropic glutamate/pheromone receptors); G alpha (i) signalling events
Gene Ontology:
Molecular function: protein binding; G protein-coupled receptor activity; glutamate receptor activity; group II metabotropic glutamate receptor activity; scaffold protein binding; calcium channel regulator activity
Biological process: G protein-coupled glutamate receptor signaling pathway; chemical synaptic transmission; negative regulation of adenylate cyclase activity; regulation of synaptic transmission, glutamatergic; adenylate cyclase-inhibiting G protein-coupled glutamate receptor signaling pathway; G protein-coupled receptor signaling pathway; modulation of chemical synaptic transmission; postsynaptic modulation of chemical synaptic transmission
Cellular component: plasma membrane; astrocyte projection; axon; dendritic spine; glutamatergic synapse; membrane; neuron projection; postsynaptic density; postsynaptic membrane; presynaptic membrane
Genetic constraint (gnomAD): Loss-of-function variants: 23 observed, 66.05 expected, observed/expected ratio (o/e) 0.35, 90% interval 0.25 to 0.49. The upper end of that interval is the gene's LOEUF score, 0.49, which puts it in group 2 of 6, group 1 being the genes least tolerant of losing a copy. Missense variants: 800 observed, 1,093.8 expected, observed/expected ratio (o/e) 0.73, 90% interval 0.69 to 0.77. Synonymous variants: 407 observed, 421.74 expected, observed/expected ratio (o/e) 0.97, 90% interval 0.89 to 1.05.
Homologues: Orthologues: chimpanzee GRM3 (99% identical), macaque GRM3 (99% identical), pig GRM3 (97% identical), mouse Grm3 (97% identical), rat Grm3 (96% identical), rabbit GRM3 (96% identical), guinea pig GRM3 (89% identical), tropical clawed frog grm3 (86% identical), zebrafish grm3 (77% identical), Caenorhabditis elegans mgl-1 (43% identical), Drosophila melanogaster mtt (42% identical), Caenorhabditis elegans mgl-3 (38% identical). Paralogues in human: GRM2 (67% identical), GRM4 (45% identical), GRM6 (45% identical), GRM7 (44% identical), GRM8 (44% identical), GRM5 (44% identical), GRM1 (43% identical).
Diseases named in the same sentence as GRM3 in open-access papers:
GRM3 is named in the same sentence as 54 diseases in open-access papers, as found by Europe PMC text mining. Sharing a sentence is not in itself a finding about the gene and the disease. The quoted sentences say what the papers report.
schizophrenia (77 papers, 2005 to 2025). A major psychotic disorder characterized by abnormalities in the perception or expression of reality. "GRM3 has been strongly validated by multiple groups as a GWAS risk gene for schizophrenia, and a reduction in GRM3-expressing dendritic spines has been observed in Alzheimer’s disease and aging." (PMID 41170381, 2025). "Cognitive disorders such as schizophrenia are also linked to alterations in the GRM3 gene that encodes mGluR3, highlighting the importance of this mechanism to human cognition." (PMID 38384333, 2024). "Activation of mGluR3 in the prefrontal cortex plays a crucial role in working memory and cognition, and genetic variations in GRM3, the gene encoding mGlu3, have been linked to schizophrenia and cognitive deficits." (PMID 38566016, 2024). "A later genome-wide association study (GWAS) recognized GRM3 as a gene containing potential schizophrenia risk variants." (PMID 36980845, 2023). "GRM3 and CACNA1c, which respectively encode G protein-coupled receptors and ion channels, are typical targets for schizophrenia drug therapy in this context." (PMID 36936681, 2023). "Alterations in mGluR3-NAAG-GCPII signaling are consistently linked to schizophrenia, where mutations to GRM3 (mGluR3) are a replicated risk factor by GWAS." (PMID 35732693, 2022). "Many genetic or inflammatory insults early in life weaken the regulation of calcium–cAMP signaling and are associated with increased risk of schizophrenia (e.g., GRM3)." (PMID 33319854, 2021). "GRM3 is a replicated GWAS risk gene for schizophrenia, and variations in FOLH1 genotype that increase GCPII expression and lower NAAG-mGluR3 signaling are associated with lower IQ scores." (PMID 34867287, 2021). "There are also important genetic links with schizophrenia risk and proteins already known to inhibit cAMP signaling in dlPFC spines, including mGluR3 (GRM3) and DISC1, which normally serves to anchor PDE4s to the spine apparatus." (PMID 33319854, 2021). "Nowadays selective ligands exist and due to the single nucleotide polymorphisms in the GRM3 gene associated with schizophrenia, interest in the target is increasing." (PMID 30897742, 2019). "The GRM3 gene was found associated to schizophrenia in large GWAS analysis (Schizophrenia Working Group of the Psychiatric Genomics Consortium, 2014) and it encodes for the mGluR3 receptor, with a prominent role in the glutamate signaling in the brain." (PMID 31040787, 2019). "Large-scale genome-wide association studies (GWAS) have identified a set of common genetic variants in glutamatergic genes in patients with schizophrenia, including, for instance, GRM3, GRIN2A, GRIA1, SRR, CLCN3, among others." (PMID 31431615, 2019). "These authors later reported that the relative abundance of GRM3Δ4 mRNA was increased in brain tissue from subjects with a GRM3 schizophrenia risk genotype." (PMID 28655286, 2017). "A transcript encoding a C-terminal variant isoform of mGlu3, GRM3Δ4, was previously identified and its expression found to be influenced by a schizophrenia-associated GRM3 risk SNP." (PMID 28655286, 2017). "Many genes associated with glutamateric neurotransmission have been previously implicated in schizophrenia, including GRM3, GRIN2A, SRR and GRIA1." (PMID 29181591, 2017). "The association between GRM3 and schizophrenia has been extensively reviewed in the past, with certain SNPs associated with deficits in working and episodic memory." (PMID 28446243, 2017). "The pathophysiological role and therapeutic potential of group II mGluRs in schizophrenia is complemented by increasing evidence that GRM3 is a risk gene for the disorder." (PMID 27130562, 2016). "These possibilities are worth pursuing, given the evidence that GRM3 contributes to the genetic risk for schizophrenia, and in light of the continuing focus on group II metabotropic glutamate receptors as therapeutic targets." (PMID 27130562, 2016).
schizophrenia (continued). "The SNP, rs10234440, is within the GRM3 locus which shows genome-wide association to schizophrenia (Schizophrenia Working Group of the Psychiatric Genomics Consortium, 2014)." (PMID 27130562, 2016). "Given the renewed, genomically-driven, focus on GRM3, the question of mGlu3 expression in schizophrenia, and its potential modulation by schizophrenia risk genotype, requires a clearer answer than the prior studies permit." (PMID 27130562, 2016). "In a recent meta-analysis of genome-wide association studies, a strong association was reported between the Grm3 locus and schizophrenia, extending prior evidence that Grm3 is involved in the genetic predisposition to psychosis." (PMID 25950516, 2015). "At the receptor level, multiple lines of evidence implicate group II metabotropic glutamate receptors in sleep regulation and photic entrainment, while there is also a robust association between the Grm3 locus and schizophrenia." (PMID 25950516, 2015). "Grm3 is also associated with bipolar disorder, and, in contrast to schizophrenia, reduced REM sleep is very common in this condition." (PMID 25950516, 2015). "We found a positive association between single nucleotide polymorphisms (SNPs) located in GRM3 and schizophrenia in the Japanese population." (PMID 24758191, 2014). "We previously performed systematic association studies of glutamate receptor gene family members with schizophrenia, and found positive associations of polymorphisms in the GRM3 (a gene of metabotropic glutamate receptor 3: mGluR3) with the disorder." (PMID 24758191, 2014). "As a replication study, our data fail to find significant associations of GRM3 with schizophrenia and depression." (PMID 24498053, 2014). "The goal of this study was to replicate the association of GRM3 with schizophrenia and depression and to explore GRM3’s potential association with heroin dependence (HD) in a Chinese population." (PMID 24498053, 2014). "In the present study, we carried out a genetic association analysis between polymorphisms in GRM3 and three types of mental disease: schizophrenia, major depression, and HD." (PMID 24498053, 2014). "Metabotropic glutamate receptor subtype 3 (mGluR3, encoded by GRM3) plays important roles in the pathophysiology of schizophrenia, depression, and drug dependence." (PMID 24498053, 2014). "Grm3 has also been associated with schizophrenia phenotypes in human genome-wide association (GWA) studies." (PMID 22511924, 2012). "The GRM3 SNPs in this study (rs6465084, rs1468412, and rs2299225) are the same as those reported to be associated with schizophrenia." (PMID 22909248, 2012). "The GRM3 gene has been mapped to 7q21.1–q21.2, spanning 220.1 kb, and is a candidate gene for susceptibility to schizophrenia." (PMID 22909248, 2012). "We sought to replicate specific findings of association between GRM3 and schizophrenia in European and European-American samples using a large, UK based case-control sample." (PMID 15892884, 2005). "The GRM3 gene (GRM3) is therefore an attractive candidate gene for schizophrenia and there have been several reports of allelic association studies examining polymorphisms in this gene." (PMID 15892884, 2005). "In a bid to attempt to provide support for GRM3 as a susceptibility gene for schizophrenia, we have genotyped those polymorphisms that have provided significant evidence in Caucasian samples in a large UK based case control sample." (PMID 15892884, 2005). "Three studies have previously reported data that were interpreted by the authors as supportive of association between schizophrenia and polymorphisms in the gene encoding the metabotropic glutamate receptor GRM3." (PMID 15892884, 2005). "However, GRM3 (the gene encoding the mGluR3 receptor) has been associated with schizophrenia and with psychosis and altered expression have been reported in the brains of schizophrenic patients." (PMID 40593462, 2025).
schizophrenia (continued). "The GRM3 gene encodes proteins that regulate neurotransmitters (e.g., glutamate) and gene mutations have been directly linked to neurological conditions such as schizophrenia." (PMID 40342962, 2025). "There have been several reports of a link between GRM3 variants and schizophrenia." (PMID 36980845, 2023). "In addition, carriers of a risk haplotype of the metabotropic glutamate receptor 3 (GRM3) for schizophrenia had lower EAAT2 expression in the prefrontal cortex as well as impaired cognitive function in respect of verbal fluency and list learning." (PMID 36980845, 2023). "Moreover, GRM3 gene, encoding mGluR3, has been pinpointed as putative harbor for schizophrenia risk variants by structural and functional GWASs60,61 and this association was confirmed by a comprehensive meta-analysis including 11,000 subjects." (PMID 35217646, 2022). "Genetic alterations in mGluR3 (GRM3) are also a replicated risk factor for schizophrenia." (PMID 34867287, 2021). "Indeed, single nucleotide polymorphisms located in Grm3 (mGlu3) or Rtn4 (Nogo-A) genes are positively associated with schizophrenia and deletion of either is known to induce related endophenotypes in mice." (PMID 30040841, 2018). "GRM3 is well-known to be implicated in the pathophysiology of schizophrenia, for instance." (PMID 30255799, 2018). "While pharmacological manipulation of group II mGlu receptors was based on the normalization of aberrant glutamatergic signaling downstream of NMDAR hypofunction, single nucleotide polymorphisms (SNPs) in the GRM3 gene encoding mGlu3 have been associated with schizophrenia in multiple studies." (PMID 28446243, 2017). "GRM3 polymorphisms associated with schizophrenia are often located in a non-coding region." (PMID 27242534, 2016). "Interestingly, recent studies found that GRM3 polymorphisms (rs1989796 and rs1476455) were associated with symptoms of refractory global psychosis in patients with schizophrenia." (PMID 24498053, 2014). "Given an OR of 1.5 at a nominal P = 0.05 for genotype frequencies ranging from 0.15 to 0.30, the statistical power of our study to detect an association of GRM3 with schizophrenia, HD, and major depression was estimated at 70.0–86.7%, 76.5–91.5%, and 68.6–85.6%, respectively." (PMID 24498053, 2014). "GRM3 polymorphisms were reported to be associated with prefrontal activity, cognitive shifting, and memory capability in healthy subjects, as well as susceptibility to schizophrenia and depression." (PMID 24498053, 2014). "Metabotropic glutamate receptor 3 (GRM3) may be associated with schizophrenia phenotype, although controversial." (PMID 22022368, 2011). "Variations in metabotropic glutamate receptor (GRM3) may be associated with schizophrenia, and has been shown to affect cortical function." (PMID 22022368, 2011). "Therefore in a bid to attempt to provide support for GRM3 as a susceptibility gene for schizophrenia, we have focussed on those polymorphisms and haplotypes that have provided significant evidence in Caucasian samples." (PMID 15892884, 2005). "This suggests that diminished GRM3 functionality, which may result in hyper-glutamatergic signalling, may cause more damage to the neurons as a result of the abnormal signaling exhibited in schizophrenia." (PMID 39734666, 2024). "For example, alterations in GRM3 are a GWAS-validated risk factor for schizophrenia and mGluR3 levels are decreased in the dorsolateral prefrontal cortex (dlPFC) of patients with schizophrenia, the cortical region needed for working memory, attention regulation and higher cognition." (PMID 35732693, 2022). "Furthermore, GRIA1 and GRM3 encoding subunits of the glutamate receptors were shared between schizophrenia and ASD, suggesting that MIA could affect glutamatergic transmission in both of these disorders." (PMID 34859219, 2021). "This variant may contribute to the mechanism by which GRM3 acts as a schizophrenia risk gene." (PMID 28655286, 2017).
schizophrenia (continued). "Genetic association analyses have consistently suggested an association between SNPs in the mGlu3R gene (GRM3) and schizophrenia including a recent multi-stage schizophrenia genome-wide association study (Schizophrenia Working Group of the Psychiatric Genomics Consortium, 2014)." (PMID 27242534, 2016). "The hypothesis that this gene may influence schizophrenia susceptibility has gained currency from the observation that homozygosity for one of the alleles of a SNP in GRM3 is associated with certain aspects of cognition that have been proposed as intermediate phenotypes for the disorder." (PMID 15892884, 2005). "In NeuN+ nuclei, several genes encoding metabotropic glutamate receptors (GRM3, GRM5) that are directly associated with schizophrenia risk were found differentially expressed in both studies." (PMID 38648100, 2024). "Pharmacological studies have discovered genes involved in the pathophysiology of schizophrenia, such as GRM3 expression in astrocytic cells, which is required to protect neurons against NMDA induced neurotoxicity." (PMID 39734666, 2024). "CACNAC1, GRIN2A, and GRM3 have already been targeted in clinical repurposing trials for schizophrenia, but these clinical trials also showed heterogeneous outcomes." (PMID 37158213, 2023). "GRM3 is a replicated GWAS hit in schizophrenia, but its relationship to cognitive dysfunction had been a mystery, as mGluR3 were generally considered to be primarily expressed in astrocytes." (PMID 33319854, 2021). "Analyses of the dlPFC from patients with schizophrenia show reduced mGluR3 and increased GCPII expression, and genetic alterations in GRM3 are associated with impaired dlPFC cognitive function." (PMID 33319854, 2021). "As previously discussed with GRM3, this link with schizophrenia comes through the dopamine receptor mediated signaling pathway, which has a total of 59 genes." (PMID 30255799, 2018). "The evidence became more compelling when the GRM3 locus was found to be genome-wide significant for schizophrenia (Schizophrenia Working Group of the Psychiatric Genomics Consortium, 2014)." (PMID 28655286, 2017). "Important schizophrenia risk variants are known to influence MMN; for example, a GRM3 variant influences its amplitude." (PMID 27450778, 2016). "Metabotropic glutamate receptor 3 (mGlu3, mGluR3), encoded by GRM3, is a risk gene for schizophrenia and a therapeutic target." (PMID 27130562, 2016). "Initially reported in candidate gene studies, the evidence is now markedly enhanced by the finding that the GRM3 locus is genome-wide significant for schizophrenia (Schizophrenia Working Group of the Psychiatric Genomics Consortium, 2014)." (PMID 27130562, 2016). "The majority of the findings suggest that the level of expression of GRM3 mRNA is unaffected in schizophrenia." (PMID 27242534, 2016). "Western blotting on membrane protein isolated from superior temporal cortex of 70 patients with schizophrenia and 87 healthy comparison subjects, genotyped for GRM3 SNP rs10234440." (PMID 27130562, 2016). "Glutamate activity in PFC has been associated with schizophrenia in numerous human studies, and converging lines of evidence suggest that Grm3 in particular influences glutamate neurotransmission, PFC function, and risk for schizophrenia." (PMID 24765068, 2014). "GRM3 is located at human chromosome 7q21.1–q21.2 and has been shown to be a promising candidate gene for schizophrenia." (PMID 24498053, 2014). "For example, Grm3 appears in all five schizophrenia gene lists extracted, presumably reflecting its strong association with the disorder in past studies." (PMID 24765068, 2014). "Three previous studies have reported positive associations between three single nucleotide polymorphisms (SNPs), rs1468412, rs6465084, and rs2299225, in GRM3 and schizophrenia in Japanese, European American, and Chinese populations." (PMID 24498053, 2014).